LAMP3 (lysosome associated membrane protein 3)
Diseases named in the same sentence as LAMP3 in open-access papers (continued):
Sharing a sentence is not in itself a finding about the gene and the disease.
esophageal squamous cell carcinoma (15 papers, 2014 to 2025). Esophageal squamous cell carcinoma (ESCC) is a type of esophageal carcinoma (EC) that can affect any part of the esophagus, but is usually located in the upper or middle third. "For example, deficiency of LAMP3 inhibited cell invasion in esophageal squamous cell carcinoma and laryngeal squamous cell carcinoma." (PMID 37878884, 2023). "Upregulation of LAMP3 expression acts as a biomarker for poor prognosis in oesophageal squamous cell carcinoma (ESCC) and ovarian cancer, whereas downregulation of LAMP3 expression has been associated with poor prognosis in hepatocellular carcinoma." (PMID 33430230, 2021). "More importantly, LAMP‐3(+) DCs stimulate the proliferation of tumor infiltrating cells CD8 which symbolizes a favorable prognosis in esophageal squamous cell carcinoma." (PMID 38022687, 2023). "Up-regulation of LAMP3 in tumor tissues has been found correlated to worse prognosis in patients with esophageal squamous cell carcinoma (ESCC)." (PMID 34568077, 2021). "LAMP3 is implied to be involved in metastasis in esophageal squamous cell carcinoma and uterine cervical cancer but in different pathways." (PMID 34993203, 2021). "We have demonstrated that LAMP3 expression level is an independent prognostic marker in esophageal squamous cell carcinoma." (PMID 26263981, 2015). "In conclusion, we have demonstrated that LAMP3 expression level is an independent prognostic marker in esophageal squamous cell carcinoma." (PMID 26263981, 2015). "Future in vivo and in vitro studies are needed to research the molecular mechanism of LAMP3 in tumorigenesis and metastasis of esophageal squamous cell carcinoma." (PMID 26263981, 2015). "In addition, high levels of LAMP3 have been identified as prognostic biomarkers in esophageal squamous cell carcinoma, hepatic and ovarian cancers." (PMID 36016386, 2022). "An evaluation of esophageal squamous cell carcinoma samples from 80 patients also found that infiltrating LAMP3+ DCs were positively correlated with intratumoral CD8+ T cells and favorable prognosis indicating a potential important role of LAMP3 in antigen presentation by DCs." (PMID 33990205, 2021). "However, epithelial expression of LAMP3 and its prognostic value in esophageal squamous cell carcinoma (ESCC) is still unknown." (PMID 26263981, 2015). "Immunohistochemistry (IHC) analysis in esophageal squamous cell carcinoma (ESCC) and primary cutaneous melanoma (PCM) revealed LAMP-3+ DCs infiltrating the peritumoral area and aggregating around CD8+ and CD25+, and OX40+ T cells, respectively." (PMID 38716077, 2024). "Although its specific function has not been identified yet, LAMP3 has been considered a biomarker of poor prognosis in tissue from esophageal squamous cell carcinoma patients." (PMID 40806007, 2025).
ovarian carcinoma (12 papers, 2017 to 2024). A malignant neoplasm originating from the surface ovarian epithelium. "CD63 also known as lysosomal associated membrane protein 3 (LAMP-3) was reported to be upregulated during melanoma, lung, and ovarian cancer conditions." (PMID 36756211, 2023). "An investigation with independent retrospective cohorts of ovarian carcinoma patients revealed that robust tumour infiltration by LAMP3+ DCs was associated with Th1 polarisation, cytotoxic activity as well as improved OS." (PMID 36808888, 2023). "Given the profound significance of LAMP3 in the progression of various gynaecological tumours including cervical, breast and ovarian cancers, this study focused on exploring the value of LAMP3 in UCEC." (PMID 38217544, 2024). "Strikingly, when comparing mRNA and protein expressions of LAMP3, levels were discernibly augmented in epithelial ovarian cancer (EOC) relative to benign tissue counterparts." (PMID 39702158, 2024). "In the meanwhile, other studies have shown that the tertiary lymphoid structure gene signature of LAMP3 can be used for prognostic prediction of ovarian cancer." (PMID 38217544, 2024). "Overexpression of LAMP3 has been found in several human cancers such as lung, colon, esophagus, breast, and ovary cancers and correlated with node metastasis by affecting cell migration." (PMID 28607528, 2017).
colorectal cancer (11 papers, 2007 to 2025). A primary or metastatic malignant neoplasm that affects the colon or rectum. "In both gastric and colorectal cancers, high LAMP3 protein expression (LAMP3+) was significantly associated with tumor stage (P=0.014 and P<0.001)." (PMID 25362357, 2014). "Activated forms of dendritic cells and macrophages in the TME have been reported as a cluster of LAMP3-positive dendritic cells in hepatocellular carcinoma and colorectal cancer and as SPP1-positive macrophages in colorectal cancer, respectively." (PMID 36550535, 2022). "In both gastric and colorectal cancer, more than 50% of cancerous tissues had high LAMP3 expression (LAMP3+), significantly higher than normal surgical margin tissues as well benign tissues." (PMID 25362357, 2014). "For LAMP3, the cutoff 120 was selected for both gastric and colorectal cancers: score 0-120 was considered low expression while 121-300 was considered high expression." (PMID 25362357, 2014). "Additionally LAMP3+ DCs can interact with T cells and NK cells, playing a crucial role in regulating lymphocytes in hepatocellular carcinoma and colorectal cancer." (PMID 39113235, 2024).
hepatocellular carcinoma (11 papers, 2020 to 2024). A malignant tumor that arises from hepatocytes. "New subsets of tumor-infiltrating lymphocytes (TILs) related to HCC have been identified, such as exhausted CD8+ T cells, exhausted Tregs, LAMP3+ dendritic cells (DCs), and tumor-associated macrophages (TAMs), gradually unraveling the immune landscape of hepatocellular carcinoma." (PMID 33043022, 2020). "For example, in hepatocellular carcinoma, LAMP3+ DCs were positively correlated with the infiltration of exhausted CD8+ T cells and Tregs." (PMID 37006307, 2023). "Meanwhile, the immunosuppressive function of LAMP3+ DCs has been validated in hepatocellular carcinoma (HCC) and non-small-cell-lung cancer (NSCLC) where LAMP3+ DCs showed strong interaction with exhausted T cells, Tregs and proliferating T cells via CD28/B7 binding and IL-15 signaling." (PMID 34568077, 2021). "A cluster of LAMP3+ DCs could migrate from hepatocellular carcinoma to LNs." (PMID 38146591, 2024). "The metastatic role of LAMP3 was also further confirmed in head and neck squamous cell carcinoma, oral squamous cell carcinoma (OSCC), and hepatocellular carcinoma (HCC) and has recently been reported as a direct target of ATF4." (PMID 33746610, 2021).
osteosarcoma (10 papers, 2018 to 2025). A usually aggressive malignant bone-forming mesenchymal neoplasm, predominantly affecting adolescents and young adults. "SPP1 is now of interest in carcinogenesis, Lysosomal-associated membrane protein 3 (LAMP3) enhances osteosarcoma cell invasion via SPP1 signaling." (PMID 36303551, 2022). "Importantly, LAMP3 has been reported to be associated with many tumor metastases, such as cervical cancer and osteosarcoma." (PMID 30008754, 2018). "LAMP3 may be associated with metastasis involving signalling downstream of SPP1 in osteosarcoma." (PMID 38146591, 2024). "We also found a population of LAMP3+ cDCs within our cohort, consistent with previous findings in osteosarcoma." (PMID 40647416, 2025). "The presence of LAMP3+ dendritic cells (LAMP3+ cDCs) or mature regulatory dendritic cells (mregDCs) has also been reported recently in various cancer types, including osteosarcoma." (PMID 40647416, 2025). "The elevated expression of CD83, CCR7, and LAMP3 in mDCs was consistent with research on osteosarcoma." (PMID 39256364, 2024). "It was also found that LAMP3 is one of the genes that are highly upregulated in osteosarcoma lung metastasis tissue than in conventional osteosarcoma tissue." (PMID 36139498, 2022). "Using multiplex fluorescence staining methods, we observed co‐localization of CD4+FOXP3+ Tregs and LAMP3+ DC in osteosarcoma tissues, which indicated the recruitment of Tregs by LAMP3_DC as previous reports." (PMID 36305631, 2022). "Our previous study showed that LAMP3 was significantly upregulated in osteosarcoma (OS) lung metastasis tissue compared to its expression in conventional OS tissue." (PMID 30008754, 2018).
lung cancer (9 papers, 2012 to 2025). A malignant neoplasm involving the lung. "In addition to genes associated with smoking the AC1/AC2 classifier included several genes implicated in lung cancer tumorigenesis, such as KITID1MMP7MYCNXRN2, and CYP24A1, as well as type II pneumocyte marker genes such as NKX2-1 (TTF1/TITF1), LAMP3 (CD208), and surfactant proteins SFTPB and SFTPC." (PMID 22676229, 2012). "In lung cancer, a study using immunohistochemistry staining found that patients who had considerably higher concentrations of CD8+ T cells and LAMP3+ DCs than those who had lower densities had prolonged OS in early stage." (PMID 36808888, 2023). "Both CD141+ DCs and CD1C+ DCs in tumors have the potential to differentiate into LAMP3+ DCs upon uptake of tumor antigens, although more CD141+ DC-derived LAMP3+ DCs have been observed in lung cancer." (PMID 37187731, 2023).
gastric cancer (8 papers, 2011 to 2024). A primary or metastatic malignant neoplasm involving the stomach. "In gastric cancer, LAMP3+ DCs were predicted to deliver attracting and activating signals to lymphocytes." (PMID 37006307, 2023). "as the involvement of LAMP3+ DC in mediating T-cell activity and with the ability to form aggregation sites for cell-to-cell interactions in the gastric cancer tumor microenvironment, from which they draw, and emphasized the possibility of targeting LAMP3 for GC." (PMID 37215115, 2023).
viral infection (7 papers, 2011 to 2023). "LAMP3 is an IFN-inducible gene, and viral infection can cause LAMP3 expression in salivary glands as the first step in the initiation of SS." (PMID 35113815, 2022). "From the perspective of virus infection, LAMP3 also participated in the replication of the influenza virus." (PMID 37006307, 2023). "Previous studies showed that LAMP3 was involved in viral infection and the formation of various biological processes." (PMID 37006307, 2023). "Further we demonstrated that knockdown of LAMP3 inhibited nuclear accumulation of influenza NP protein at early stages of viral infection." (PMID 21810281, 2011). "Confocal microscopy results demonstrated that viral NP is colocalized within LAMP3 positive vesicles at early stages of virus infection." (PMID 21810281, 2011). "Furthermore, in other viral infections, e.g., hepatitis C virus and human papillomavirus, LAMP3 is also specifically induced as a classical interferon-stimulated gene." (PMID 37006307, 2023). "It colocalizes with LAMP3 throughout the course of viral infection, from early endosomes to late endosomes and lysosomes, and depletion of LAMP3 significantly reduces HSV-2 entry into VK2 cells and subsequent passage to the intracellular compartments needed for replication." (PMID 36350153, 2022). "In the virus infected cells, part of the LAMP3 translocated from the cytoplasm to the plasma membrane, suggesting that virus infection may regulate LAMP3 trafficking." (PMID 21810281, 2011). "We next determined if the localization of LAMP3 changes upon virus infection." (PMID 21810281, 2011). "Therefore, the expression of LAMP3 is involved in various viral infections and tumor prognoses." (PMID 37006307, 2023). "Tetraspanins, including LAMP3/CD63, are key players in HIV entry and release and also play critical roles at different steps in the viral infection cycle." (PMID 36350153, 2022). "Since our results showed that LAMP3 influences overall infection and replication of HSV-2, we decided to examine the different stages of viral infection and replication in more detail." (PMID 36350153, 2022). "Other B lymphocyte markers such as Blimp1, Pax5, or markers related with antigen presentation cells like MHC-II or Lamp3 showed no significant regulation due to viral infection at the time periods studied." (PMID 25338079, 2014). "Finally, we determined the protein expression level of LAMP3 in A549 cells and IFN-deficient Vero cells, and the results demonstrated that, upon viral infection, LAMP3 protein was upregulated in A549 cells but not in Vero cells, indicating that LAMP3 induction may be interferon-dependent." (PMID 21810281, 2011).
influenza (6 papers, 2011 to 2024). An acute viral infection of the respiratory tract, occurring in isolated cases, in epidemics, or in pandemics; it is caused by serologically different strains of viruses (influenzaviruses) designated A, B, and C, has a 3-day incubation period, and usually lasts for 3 to 10 days. "IRF7 and LAMP3 are members of our influenza and vaccination biologically significant gene lists, while DPF2 was statistically significant with respect to disease state." (PMID 31787983, 2019). "By confocal microscopy, the cytoplasmic speckles of influenza NP colocalized within the LAMP3 positive vesicles, indicating that LAMP3 may be involved in influenza endocytosis or vRNP trafficking pathways." (PMID 21810281, 2011). "Knockdown of LAMP3 expression by RNA interference inhibits viral replication in the early stage, suggesting that LAMP3 may play an important role in influenza life cycles." (PMID 21810281, 2011). "The mechanistic role of host expressed genes in influenza has been investigated using knockdown experiments including genes such as IRF7, LAMP3, and DPF2 which in our study were differentially expressed in either influenza, vaccine or both." (PMID 31787983, 2019). "They found that interferon-related genes such as RSAD2, LAMP3, IFI44L, and OAS1 were significantly differentially expressed in individuals with symptomatic RSV, influenza, or HRV infection." (PMID 24265599, 2013). "scRNA-seq analysis at 28 days after influenza infection shows that Sox2 lineage-traced cells can generate bona fide AT2 cells, as indicated by expression of canonical AT2 markers such as Sftpc and Lamp3, but with very low levels of secretory cell markers such as Scgb1a1." (PMID 38182591, 2024). "While none of these six genes were amongst the best discriminators of respiratory syncytial virus (RSV) from influenza, four of the six genes (OAS3, SEPT4, LAMP3 and RPT4) were represented in a gene list of 161 interferon-related differentially expressed genes." (PMID 25345603, 2015).
Sjögren’s syndrome (6 papers, 2020 to 2025). "Little is known about the role of LAMP3 in disease, although an association between LAMP3 expression and serum auto-antibodies in Sjögren’s syndrome was found." (PMID 36189218, 2022). "The increase in LAMP3 expression is associated with the development of Sjögren’s Syndrome (SS)." (PMID 40297850, 2025). "In this study, aggregation of unbiased transcriptome profiling data sets of minor salivary gland biopsies from controls and Sjögren’s syndrome patients identified increased expression of lysosome-associated membrane protein 3 (LAMP3/CD208/DC-LAMP) in a subset of Sjögren’s syndrome cases." (PMID 32939030, 2020). "The European League against Rheumatism Sjögren’s syndrome disease activity index (ESSDAI) was significantly decreased after HCQ treatment in both the high-LAMP3 group (5.0 ± 2.9 to 1.4 ± 2.2, P < 0.05) and normal-LAMP3 group (5.9 ± 3.4 to 2.2 ± 3.2, P < 0.01)." (PMID 36821638, 2023). "In addition this increase in LAMP3 led to the release of common Sjögren’s syndrome autoantigens via extracellular vesicles in caspase-independent manner, identifying a potential mechanism involved in their antigenicity." (PMID 32939030, 2020). "Interestingly, LAMP3 expression resulted in the accumulation and release of intracellular TRIM21 (one component of SSA), La (SSB), and α-fodrin protein, common autoantigens in Sjögren’s syndrome, via extracellular vesicles in an apoptosis-independent mechanism." (PMID 32939030, 2020).
COVID-19 (5 papers, 2021 to 2026). A disease caused by infection with severe acute respiratory syndrome coronavirus 2. "With our own findings coinciding with the current literature, LGALS9, LAMP3, PRSS8 and AGRN prove to be potential biomarkers of health risk in COVID-19 patients, both individually and collectively." (PMID 39334929, 2024). "Strikingly, a significantly elevated percentage of LAMP3+ DCs could be observed in the BALF of six severe COVID-19 cases in comparison to cells from healthy controls or mild to moderate COVID-19 patients." (PMID 35832091, 2022). "Interestingly, we observed a significantly reduced capacity of COVID-19 platelets to increase the expression of the activation markers LAMP-3 and P-Selectin (p = 0.04 and p = 0.04, respectively) upon stimulation." (PMID 33414384, 2021). "However, we observed a significantly reduced capacity of COVID-19 platelets to increase the expression of activation markers LAMP-3 and P-Selectin upon stimulation with TRAP." (PMID 33414384, 2021). "In conclusion, our study demonstrates that LGALS9, LAMP3, PRSS8 and AGRN are highly significant, differentially regulated plasma proteins found in hospitalised COVID-19 patients." (PMID 39334929, 2024). "FSTL3 has been implicated as a marker of COVID-19—CVD complications; however, no SNPs were found to be significantly correlated with hospitalisation for LGALS9, LAMP3, PRSS8 or AGRN." (PMID 39334929, 2024). "After activation, we detected significantly higher levels of platelet activation markers P-Selectin and GPIIb/GPIIIa complex but not LAMP-3 in COVID-19 patients compared to healthy controls." (PMID 33414384, 2021). "Our results also coincide with these published findings and show that LGALS9, LAMP3 and PRSS8 are more expressed in hospitalised COVID-19 patients compared to non-hospitalised ones and demonstrated its utility as a predictive biomarker of health risk." (PMID 39334929, 2024).
psoriasis (5 papers, 2007 to 2025). An autoimmune condition characterized by red, well-delineated plaques with silvery scales that are usually on the extensor surfaces and scalp. "We found a significantly increased number of LAMP3+ cDCs in the skin of classical psoriasis as compared to skin from healthy donors." (PMID 29295985, 2018). "In addition, the SFRP2+ inflammatory fibroblasts in psoriasis share with the COL6A5+COL18A1+ fibroblasts in atopic dermatitis the expression of CCL19 which is capable of recruiting CCR7+LAMP3+ cDC2A61." (PMID 37308489, 2023). "In contrast, there were significantly fewer LAMP3+ cDCs in paradoxical psoriasis suggesting a lack of cDC maturation despite the increase type I IFN expression." (PMID 29295985, 2018).